ENSG00000279284 ( gene)
Diseases named in the same sentence as ENSG00000279284 in open-access papers (continued):
Sharing a sentence is not in itself a finding about the gene and the disease.
tumor (continued). "Classical protein tyrosine phosphatase nonreceptor type 12 (PTPN12) has been extensively studied to decipher its mechanism as a tumor suppressor gene in various human carcinomas; however, there is no comprehensive elucidation of the PTPN12 expression and its regulatory mechanisms in LSCC." (PMID 37333450, 2023). "However, PAG1 can be considered an oncogene or a tumor suppressor gene, depending on tumor type, and its expression is not homogeneous across the different types of cancers." (PMID 34141616, 2021). "Finally, we illustrated that the effect of AOX1 as a tumor suppressor gene is not restricted to ccRCC but universally exists in many other cancer types." (PMID 34290740, 2021). "The mitotic checkpoint gene, BUB1, may also drive tumor metastasis and progression." (PMID 26096802, 2015). "Notably, MT1G could not be simply identified as a tumor suppressor gene or oncogenic gene in ccRCC, but MT1G seemed to play a dual role in the development and progression of tumors." (PMID 36204178, 2022). "However, the reduced expression level of CAV1 in EOC cells compared to noncancerous tissues may point to a role for CAV1 as a tumor suppressor gene." (PMID 32401768, 2020). "In our research, the reduction in expression levels of WISP1 was observed in the TS group compared with the NS group, which suggested that WISP1 may act as a tumor suppressor gene in MD-induced tumorigenesis, unlike its oncogenic role in many kinds of human cancers and cell lines." (PMID 30922224, 2019). "However, because the available probe in the validation set proved to be not specific to PTEN, we could not confirm its frequent involvement as a tumor suppressor gene in this set." (PMID 25551557, 2014). "Furthermore, Notch mutation study of head and neck squamous cell carcinomas also suggests that Notch1 may function as a tumor suppressor gene rather than an oncogene in this tumor." (PMID 23409141, 2013). "For example, the EphB2 receptor has been presented as a putative tumor suppressor gene in PCa, whereas the EphB4 receptor is known to be both tumor-promoting in the presence of its cognate ligand Ephrin B2 (EFNB2) and a tumor suppressor in the absence of EFNB2." (PMID 35565468, 2022). "Although downregulation of tumor suppresser WWOX expression has frequently been reported in various types of cancers, Wwox deletion did not necessarily increase the proliferation or development of premalignant lesions, suggesting that WWOX is not a classical tumor suppressor gene." (PMID 27234396, 2013).
cancer (197 papers, 2008 to 2026). A tumor composed of atypical neoplastic, often pleomorphic cells that invade other tissues. "S100A6 is an important calcium signal-regulating gene, and the calcium-binding protein it encodes is a member of the S100 family, which is associated with DNA damage and a variety of cancers." (PMID 36232318, 2022). "XRCC2, a homologous recombination-related gene, has been reported to be associated with a variety of cancers." (PMID 34051735, 2021). "ARID1A, an SWI/SNF chromatin-remodeling gene, usually is mutated in cancer and is considered to be capable of suppressing tumors." (PMID 33771191, 2021). "Supporting this it has been shown that in ~2.5% of all cancer, a germline mutation in a DNA repair gene was associated with cancer development." (PMID 32850380, 2020). "The B cell lymphoma/leukemia-2 gene (BCL2) and the Bcl2-associated X protein gene (BAX) are an oncogene and a cancer suppressor gene, respectively." (PMID 24459422, 2013). "Additionally, PSMD1 is classified as an innate immune gene, and its up-regulation is strongly associated with the progression of different types of cancers." (PMID 38933262, 2024). "Mtss1 is well-known to act as a tumor suppressor gene in different types of cancer since it controls cell proliferation, migration, invasion and metastasis of cancer cells by regulating actin dynamics and signalling pathways." (PMID 41288860, 2025). "Combined with our findings, PNPLA7 is likely to be a cancer suppressor gene that acts as a promising biomarker in various tumors." (PMID 40221501, 2025). "Conversely, senescent cancer cells treated with WEW exhibited an opposite effect on the expression of the pro-inflammatory gene." (PMID 38696307, 2024). "Recent studies have shown that most natural compounds reduce chemoresistance by inhibiting the expression of the multi-drug resistance gene (MDR) or reducing MDR protein activity in cancer cells." (PMID 36006482, 2023). "On the other hand, we also confirmed that p16 (a cancer suppressor gene) was a downstream target of H3K4me3, the promoter of which can directly bind to H3K4me3." (PMID 36866240, 2023). "As a metastasis‐suppressor gene in many other cancers, SCN4B also inhibited the progression of LUAD." (PMID 37826914, 2023). "MT1G is a DNA methylation-related gene which is reported to play an important role in various types of cancer." (PMID 35167648, 2022). "It acts as an oncogene in some cancers, while functioning as a cancer-suppressor gene in the other cancers." (PMID 36188536, 2022). "As a serine/threonine protein kinase, DAPK1 is considered to be a cancer suppressor gene, which is regulated by calmodulin (CaM) and is a positive regulator of IFN-γ-induced apoptosis." (PMID 35321516, 2022). "XRCC1 is a DNA repair gene that plays a crucial role in maintaining genomic integrity and stability and in the pathogenesis and carcinogenesis of various type of cancer." (PMID 33868991, 2021). "CCND1 was frequently overexpressed in various kinds of human cancers as a well-known cancer-related gene." (PMID 33996561, 2021).
cancer (continued). "Supporting our notion, CEP131 has been recently recognized as an important cancer-related gene in several human malignancies." (PMID 33014050, 2020). "Previous studies have shown that TXNIP is a cancer suppressor gene in numerous solid tumors and hematological malignancies." (PMID 33106166, 2020). "Considering that the activity of this DNA repair gene is related to the progression of cancer, it is necessary to evaluate the DNA repair ability of cancer cells when chemotherapy is contemplated for cancer patients." (PMID 33261027, 2020). "Approximately 10% of all cancers show a focal amplification of chromosome 1q21.2, a region harboring the antiapoptotic gene MCL1." (PMID 31266530, 2019). "KLF4 is a dual-function transcription factor, which can exert its role as an oncogene or a tumor suppressor gene depending on the cancer type or cancer stage." (PMID 30297986, 2018). "Studies have documented that activation of a DNA repair gene MTH1 is required for cancer cells to block incorporation of oxidized dNTPs and thereby prevent ROS-induced DNA damage." (PMID 28261604, 2017). "It is widely known that miRNA is important as an oncogene or a tumor suppressor gene depending on the subtypes of a particular cancer." (PMID 27304060, 2016). "Despite an increasing body of evidences is highlighting PATZ1 as a cancer-related gene, little is known about its function." (PMID 25595894, 2015). "This provide further evidence that miR-449a has a similar function to that of a cancer suppressor gene." (PMID 25202363, 2014). "Finally, we realized that COL11A1 has been identified as a potential metastasis-associated gene in other types of cancer as well, such as in lung, and oral cavity, suggesting that the MAF signature may be present in a subset of high stage samples of most if not all epithelial cancers." (PMID 21047417, 2010). "Given that both hypoxia and PLOD2 play critical roles in α-promoter-preferred DCLK1 activation, and that PLOD2 is a known a hypoxia-responsive gene in multiple cancers, we hypothesized that PLOD2 mediates hypoxia-induced activation of DCLK1-L." (PMID 40775208, 2025). "It has been identified as a cancer suppressor gene in some cancers." (PMID 38191448, 2024). "The novel pleiotropic gene WWOX is a cancer suppressor gene that could induce apoptosis and inhibit growth in various cancers." (PMID 38259487, 2023). "Serpine1 is a known hypoxia-sensitive gene, as reported in a previous study on cancer cells." (PMID 37432746, 2023). "Rad51, a DNA-repair-related gene, has been reported to be involved in multiple cancers." (PMID 34115569, 2021). "Studies suggested that Egr1 was a cancer suppressor gene and transcriptional regulator." (PMID 33479397, 2021). "MIF has been identified as a hypoxia-induced gene in cancer cells." (PMID 20727156, 2010). "In the first example, ERCC2 (also known as XPD) is a cancer-related gene." (PMID 20015360, 2009). "ATM, a DNA repair gene, is associated with various cancers but not previously linked to HCC." (PMID 41146957, 2025). "Finally, regarding the implications of p38β in cancer biology, it is important to mention that Stress Activated Protein Kinases signaling pathways, JNK and p38MAPK, have been shown to play a dual role in cancer, both as an oncogene and as a tumor suppressor gene." (PMID 33053909, 2020).
cancer (continued). "SMARCA1, a chromatin remodeling gene, has been reported to stimulate steroidogenic acute regulatory (StAR) protein expression through association with the StAR promoter, and SMARCA1 knockdown causes significant growth inhibition and induces apoptosis of cancer cells." (PMID 22272226, 2012). "The importance of balancing opposing activities in cancer is illustrated by genes such as HEF1 (NEDD9), a metastasis-related gene and HMMR, a gene involved in centrosome formation." (PMID 18636107, 2008). "In other cancers, MXRA5 has also been shown to be a cancer-promoting gene." (PMID 40002669, 2025). "The growth-inhibitory imprinted gene Peg3 is not expressed by C26 cells, which is highly relevant since loss of Peg3 expression through promoter methylation, loss of heterozygosity and other mechanisms may stimulate clonogenic growth and contribute to the pathogenesis of a number of cancers." (PMID 20615237, 2010). "Expression of Peg3, a growth-inhibitory imprinted gene which is frequently down-regulated in cancer, was absent (data not shown)." (PMID 20615237, 2010). "Using a novel genomic approach, we identified a 48-gene “Poised Gene Cassette” (PGC) showing tight regulation specifically in human cancers but not in corresponding nonmalignant tissues." (PMID 18636107, 2008).
infection (20 papers, 2006 to 2025). The state of being infected such as from the introduction of a foreign agent such as serum, vaccine, antigenic substance or organism. "In this study, we showed that another RpoS-regulated gene bb0689, as a novel virulence gene encoding an outer surface lipoprotein, contributes to the optimal infection of B. burgdorferi in animals." (PMID 39679711, 2025). "The homeobox gene egl-5 acted downstream of β-catenin/bar-1 to regulate the innate immune response to pathogenic infection." (PMID 36120363, 2022). "We also found that the SPβ-like phage Φ3T has a counter-defense gene that prevents SpbK-mediated abortive infection and enables the phage to produce viable progeny, even in cells expressing spbK." (PMID 40173202, 2025). "Its overexpression was shown to facilitate infection by rice black-streaked dwarf virus in Laodelphax striatellus (Fallén) through the suppression of the immune-related gene Ken." (PMID 40429173, 2025). "Increased direct antigen presentation compared to infection with the WT virus is achieved by deletion of the immune evasion gene m152 in virus mCMV-Δm152." (PMID 38149242, 2023). "In the present study, through the identification of the fungal virulence gene VdDpb4 from V. dahliae, we found that VdDpb4 is essential for the V. dahliae development and infection, including tolerant toward ROS stress during development and plant infection." (PMID 32298394, 2020). "The gene encoding PTS1 of C albicans and the cyb2 gene of C. glabrate were identified as a novel virulence gene or adaptive gene, respectively, in fungi based on screening the fungal mutants using the silkworm infection models." (PMID 28947778, 2017). "However, the salicylic acid-responsive defense gene and the jasmonic acid-responsive gene were induced more rapidly in Met-treated plants after infection with Pst and Bc, respectively." (PMID 38928022, 2024). "The discovery that production of these phytohormones is controlled by an hrp master regulatory gene whose activity is induced in presence of plant cells strongly suggests that these molecules play a key role during the early steps of infection in addition to the TTSS." (PMID 16933989, 2006). "Similar to results with lytic genes RTA, ORF49, K2 (vIL6), K14 (vOX2), ORF25, ORF36, latent gene LANA, or GFP, all lytic and latent genes expressed at higher levels following KSHV, as compared to KSHVΔLANA infection, at 72 hpi." (PMID 38232124, 2024). "A quantitative real-time PCR (qRT-PCR) assay was used to assess the expression of the Fov infection-related gene FOTG, and we found evidence of infection 28 h after inoculation." (PMID 30814537, 2019). "The infection of Sf9 cells revealed that deletion of the amino acids 91–173 of LEF-6 did not severely affect virus production, but the fluorescence intensity of GFP representing the expression of viral late gene was significantly reduced." (PMID 40787986, 2025). "GAPDH was used as a house-keeping gene, which displayed a non-coherent expression likely due to either the heterogeneous cell population found in the CP tissue or lower RNA integrities compared to RNA from the in vitro infection experiments." (PMID 33763387, 2021). "Taken together, this study has revealed that gene expression of the putative virulence gene B22R is a potential early marker of SGPV infection, detectable already after one day, and that hydrocortisone injection suppresses antiviral immune responses to SGPV during early infection." (PMID 34177946, 2021). "Harmine acted as an anti-infection agent mainly by inhibiting the transcription and expression of the T3SS regulatory gene hilA, and it did not affect S. Typhimurium growth." (PMID 36176578, 2022).
bacterial infection (1 paper, 2022). "Gene vom1 prevents the yolk from mixing with the albumen and protecting the egg from bacterial infection." (PMID 36498889, 2022).
ENSG00000279284 also shares sentences with these, for which no sentence is quoted: endometrial cancer (3 papers); nasopharyngeal carcinoma (3); Wilms tumor (3); acute lymphoblastic leukemia (2); Anxiety (2); cardiac arrhythmia (2); Cerebral ischemia (2); head and neck cancer (2); lymphoma (2); malaria (2); Multiple Myeloma (2); papillary thyroid cancer (2); psoriasis (2); retinal degeneration (2); Achalasia-Addisonianism-Alacrima syndrome (1); atherosclerosis (1); atrial fibrillation (1); benign tumors (1); blood disease (1); bone tumors (1); cervix (1); childhood leukemia (1); cholera (1); co-infection (1); Congenital adrenal hypoplasia (1); COVID-19 (1); cutaneous squamous cell carcinoma (1); dermatomyositis (1); diffuse astrocytoma (1); eczema (1).
A further 45 diseases each share a sentence with ENSG00000279284 in 1 paper.